PINK1 (PTEN induced kinase 1)
Diseases named in the same sentence as PINK1 in open-access papers (continued):
Sharing a sentence is not in itself a finding about the gene and the disease.
osteosarcoma (continued). "These partial experiments support that cisplatin may promote apoptosis of U2OS cells by downregulating PINK1, thus playing a role in killing osteosarcoma cancer cells." (PMID 36823640, 2023). "More importantly, in osteosarcoma, the high expression of PINK1 suggests a worse prognosis." (PMID 36823640, 2023). "The role of PINK1 in cancers such as osteosarcoma is still unclear." (PMID 36823640, 2023). "However, we found that PTEN expression is repressed in osteosarcoma, while PINK1 expression is promoted." (PMID 36823640, 2023). "Consistently, PINK1 might act as a tumor suppressor in osteosarcoma, as RNA‐Seq data showed that the mRNA level of PINK1 was decreased in osteosarcoma tissues compared with normal tissues and a high level of PINK1 predicted a good survival rate for osteosarcoma patients." (PMID 36529692, 2023). "Furthermore, we found that FOXO3a was markedly increased in osteosarcoma tissues compared with adjacent tissues, suggesting that overexpression of PINK1 might be regulated by FOXO3a." (PMID 36823640, 2023). "However, the biological function and related mechanisms of PINK1 in osteosarcoma remain unknown." (PMID 36823640, 2023). "In this study, we found that PINK1 was upregulated in osteosarcoma and that FOXO3a rather than PTEN modulated its expression." (PMID 36823640, 2023). "FOXO3a, rather than PTEN, upregulates the expression of PINK1 in osteosarcoma." (PMID 36823640, 2023). "However, no study has reported the correlation between PINK1 and chemotherapy drugs in osteosarcoma." (PMID 36823640, 2023). "Additionally, we found that PTEN was reduced, while FOXO3a was markedly increased in osteosarcoma, suggesting that FOXO3a and not PTEN induced the overexpression of PINK1." (PMID 36823640, 2023).
small cell lung carcinoma (6 papers, 2024 to 2025). Small cell lung cancer (SCLC) is a highly aggressive malignant neoplasm, accounting for 10-15% of lung cancer cases, characterized byrapid growth, and early metastasis. "The m6A methyltransferase METTL3 contributes to chemoresistance in small cell lung cancer by activating PINK1-PRKN-mediated mitophagy." (PMID 40855568, 2025). "METTL3-mediated m6A modification of uncapped mRNA2235 (DCP2) triggers its degradation, and promotes mitosis and chemoresistance in small cell lung cancer (SCLC) cells through the PINK1/Parkin pathway." (PMID 40786181, 2025). "It has been reported that PINK1-Parkin pathway-mediated mitophagy and mitochondrial damage promote chemotherapy resistance in small cell lung cancer (SCLC) patients." (PMID 39828712, 2025). "METTL3 induces the degradation of decapping protein 2 (DCP2), resulting in reduced inhibition of PINK1 and Parkin with enhanced mitophagy, alleviated tumor cell dysfunction levels and increased chemotherapy resistance in small cell lung cancer (SCLC)." (PMID 41373022, 2025). "METTL3 induces m6A methylation by promotes mitochondrial autophagy through the Pink1-Parkin pathway, leading to chemotherapy resistance in small cell lung cancer." (PMID 39010105, 2024). "High plasma PINK1.AS levels in small cell lung cancer patients predicted distant metastasis." (PMID 38326441, 2024).
Autoimmunity (5 papers, 2018 to 2023). The occurrence of an immune reaction against the organism's own cells or tissues. "Recently, E. coli has also been shown to cause PD-like motor symptoms in Pink1-/- mice and to produce mitochondria-specificauto-reactive CD8+ T cells via MitAP, causing autoimmunity in DA neurons." (PMID 36467550, 2022). "In addition, besides MNRR1, a number of other nDNA-encoded mitochondrial proteins such as GSTP1, PINK1, SPATA5 and MFF have been implicated in BC progression or BC risk, suggesting that mitochondrial autoimmunity prominently participates in breast carcinogenesis." (PMID 33615312, 2020). "The reduced ability of PINK1−/− CD4+ T cells to suppress bystander T cell proliferation indicate that this pathological state could result in reduced immuno-surveillance or activated autoimmunity during PD progression." (PMID 30319601, 2018). "Absence of PINK1/Parkin leads to the mitochondrial aberrations by triggering immune system disorders (reduced immuno-surveillance or activated autoimmunity)." (PMID 30319601, 2018). "As previously stated, elucidating the abnormal function of T cells in the absence of PINK1 and/or Parkin may also help to unravel the role of autoimmunity in PD." (PMID 30319601, 2018).
brain injury (5 papers, 2021 to 2026). Acute and chronic (see also brain INJURIES, CHRONIC) injuries to the brain, including the cerebral hemispheres, CEREBELLUM, and brain STEM. "Increased expression of PINK1/Parkin in brain trauma models can improve mitophagy, inhibit pyroptosis, and play a neuroprotective role." (PMID 40016173, 2025).
endometriosis (5 papers, 2020 to 2025). The growth of functional endometrial tissue in anatomic sites outside the uterine body. "Mitophagy proteins Pink1 and Parkin, as well as Bcl-2 family proteins activation, would reduce endometriosis development." (PMID 34064854, 2021). "Furthermore, the PINK1-Parkin mitophagy pathway represents a critical mechanism by which macrophage stimulator 1 (Mst1), a negative regulator of endometriosis, modulates apoptosis and migration in human endometrial stromal cells (ESCs)." (PMID 41341128, 2025). "Decreased levels of PINK1 are noted in the endometrium with minimal and mild endometriosis." (PMID 35563743, 2022).
glaucoma (5 papers, 2019 to 2025). Increased pressure in the eyeball due to obstruction of the outflow of aqueous humor. "This study determined the role of MMF in preventing mitochondrial autophagy related to pressurization-induced death of RGCs through the regulation of the Pink1/Parkin pathway, and investigated the underlying mechanism to provide a theoretical basis for the clinical treatment of glaucoma." (PMID 39792763, 2025). "Finally, we will discuss PINK1/PARKIN gene augmentation possibilities with a particular focus on AD, PD and glaucoma." (PMID 33168089, 2020).
kidney damage (5 papers, 2019 to 2025). "For instance, phthalates have been linked to kidney damage through mechanisms involving PINK1/Parkin-mediated mitophagy and mitochondrial energy deficiency." (PMID 39722714, 2024). "Notoginsenoside R1 and germacrone enhance PINK1-dependent pathways in retinopathy and nephropathy, while Huangqi-Danshen decoction and hyperforin activate STING1/PINK1 or DLAT-AMPK axes to bolster autophagic flux." (PMID 40866350, 2025). "Taken together, it was probable that PINK1 deficiency caused a compensatory increase of Parkin and affected DRP1 dependent mitochondrial fission to protect against mitochondrial fragmentation, mitophagy and overall kidney damage." (PMID 31607953, 2019).
kidney injury (5 papers, 2018 to 2022). Trauma to the kidney. "Among the three BMSC intervention groups (the BMSC group, OE PINK1 group and Anti-PINK1 group), the OE PINK1 group had the most moderate kidney injury, followed by the IRI group, and the Anti-PINK1 group had the most serious kidney injury." (PMID 35962179, 2022). "In nephrotoxic models, our current study and the work by Yuan’s laboratory also support a protective role of PINK1/Parkin-mediated mitophagy in cisplatin-induced kidney injury." (PMID 30385753, 2018). "Similarly, PINK1/Parkin-mediated mitophagy might have a positive effect on acute LPS-induced kidney injury." (PMID 34025411, 2021). "The down-regulation of PINK1 and Parkin indicated that PINK1/Parkin pathway might not take the major responsibility for the active of mitophagy in cisplatin-induced kidney injury." (PMID 31607953, 2019).
Lewy Body Disease (5 papers, 2021 to 2025). "Heterozygous variants in PINK1 (including the PINK1 rs1043424 variant) have also been detected in patients affected by early-onset AD and Lewy Body Disease, although the role of PINK1 in the susceptibility to these disorders is yet to be clarified." (PMID 36361641, 2022). "There is also overlap in splicing changes between the PINK1 mutant hPSC-derived mDA neurons and many of the transcript isoforms altered in all three Lewy body diseases." (PMID 40950074, 2025). "While PINK1-KO rats do not develop Lewy bodies per se, the accumulation of α-synuclein aggregates is a proxy for Lewy bodies in humans with PD and Lewy Body Dementia." (PMID 36614135, 2022).
lung squamous cell carcinoma (5 papers, 2020 to 2025). "Our analysis revealed that high PINK1 mRNA levels in lung squamous cell carcinoma or OPTN in thyroid cancer are associated with improved survival." (PMID 39859167, 2025). "There were contradictory results between liver hepatocellular carcinoma and lung squamous cell carcinoma in the correlations of PINK1 expression with immune infiltration, including infiltration of B cells, CD8+ T cells, CD4+ T cells, macrophages, neutrophils, and dendritic cells." (PMID 33244455, 2020). "Conversely, in lung squamous cell carcinoma (LUSC) and PAAD, elevated PINK1 expression corresponds to poorer survival outcomes, suggesting a pro-oncogenic function in these contexts." (PMID 40565152, 2025). "In TIMM23-knockdown human embryonic kidney 293 T (HEK293T) cells, undegraded PINK1 accumulated, whereas TIMM23 expression remained unchanged in lung squamous cell carcinoma cell lines H226 and H520 despite variations in BRF2 and SLC8A3 levels." (PMID 40610422, 2025). "In contrast, a high expression level of PINK1 was negatively correlated with both OS and DFS in HNSC (head and neck squamous cell carcinoma) and LUSC (lung squamous cell carcinoma)." (PMID 33244455, 2020). "Notably, diffuse cytoplasmic expression of Pink1 in lung squamous cell carcinoma (SQCC) contrasts with the granular cytoplasmic pattern in normal lung tissues, implicating aberrant Pink1 expression in lung carcinogenesis." (PMID 38962310, 2024).
non-alcoholic fatty liver disease (5 papers, 2021 to 2024). "Bge., alleviates non-alcoholic fatty liver disease by enhancing PINK1/Parkin-dependent mitophagy in oleate/palmitate-induced HepG2 cells and high-fat diet-fed mice." (PMID 34414181, 2021). "In mice livers, PINK1-mediated mitophagy was shown to have a protective role against non-alcoholic fatty liver disease (NAFLD) by clearing damaged mitochondria and allowing cyanidin-3-O-glucoside (C3G) to suppress oxidative stress, NLRP3 inflammasome activation and improving glucose metabolism." (PMID 34198743, 2021).
periodontitis (5 papers, 2022 to 2025). An acute or chronic inflammatory process that affects the tissues that surround and support the teeth. "Here, we showed that PINK1 deficiency exacerbated periodontitis by promoting inordinate osteoclast formation." (PMID 38181706, 2024). "We also verified the in vivo role of PINK1 in osteoclastogenesis control by experiments with a periodontitis-associated bone loss model." (PMID 38181706, 2024). "Together, these results indicate that PINK1 deficiency aggravates alveolar bone loss induced by experimental periodontitis in mice." (PMID 38181706, 2024). "In addition, treatment with NAC reduced osteoclast overproduction induced by PINK1 deficiency, thereby delaying periodontitis progression." (PMID 40861497, 2025). "Taken together, targeting PINK1 to prevent overstimulation of osteoclastogenesis may provide a novel therapeutic strategy not only for periodontitis but also for other age-associated skeletal diseases." (PMID 38181706, 2024). "Since PINK1 deficiency aggravated periodontitis, we next investigated whether PINK1 has a direct role in osteoclast differentiation and function." (PMID 38181706, 2024). "Nevertheless, our findings indicate that PINK1 is essential for regulating mitochondrial quality during osteoclast differentiation, whereby loss of PINK1 can lead to mitochondrial abnormalities, followed by excessive osteoclastogenesis and exacerbation of periodontitis." (PMID 38181706, 2024). "Here we aimed to determine whether PINK1 plays a role in the regulation of osteoclastogenesis and alveolar bone resorption associated with periodontitis." (PMID 38181706, 2024). "We speculated that in diabetic patients, low expression of PINK1 gene is closely related to the high risk of periodontitis." (PMID 35473620, 2022). "Both Pink1 WT-LIP and Pink1 KO-LIP groups displayed typical features of periodontitis upon ligature placements." (PMID 38181706, 2024). "In this study, we investigated the function of PINK1 in osteoclast differentiation and periodontitis by using Pink1 knock-out (KO) mice." (PMID 38181706, 2024). "Although, its role in M1 polarization in periodontitis requires further investigation, here we clearly showed a direct role of PINK1 in osteoclast differentiation and function." (PMID 38181706, 2024). "C57BL/6 wild type (WT) and Pink1 knockout (KO) mice were subjected to ligature-induced periodontitis (LIP), and alveolar bones were evaluated by μCT-analysis and tartrate-resistant acid phosphatase (TRAP) staining." (PMID 38181706, 2024). "Compared with the periodontitis rats, the antibody expression (PINK1 and Parkin) was significantly up-regulated in the MitoQ@PssL NPs treated rats." (PMID 36588945, 2022). "This suggests that PINK1 is able to maintain normal mitochondrial morphology, stabilize mitochondrial membrane potential and reduce mtROS production, thereby inhibiting the overproduction of periodontitis osteoclasts in periodontitis." (PMID 40861497, 2025). "Pink1 KO mice developed severe periodontitis upon ligature placement." (PMID 38181706, 2024). "Therefore, targeting PINK1 may provide a novel therapeutic strategy for severe periodontitis with fulminant osteolysis." (PMID 38181706, 2024). "Thus, it cannot be excluded that genetic deletion of Pink1 may exert detrimental effects on periodontitis via M1 polarization through the cGAS-STING pathway." (PMID 38181706, 2024). "Therefore, we could not rule out the effects of PINK1 deficiency on innate immune responses in ligature-induced periodontitis." (PMID 38181706, 2024).
prion disease (5 papers, 2021 to 2024). A transmissible disease that is caused by a protein that is able to induce abnormal folding of normal cellular proteins, leading to characteristic spongiform brain changes, which are associated with neuronal loss without an inflammatory response. "The PINK1/Parkin pathway of mitophagy has been implicated in multiple neurodegenerative diseases including prion diseases." (PMID 38394123, 2024). "Using prion disease cell models, we observed PINK1-parkin-mediated mitophagy deficiency in which parkin depletion aggravated blocked mitochondrial colocalization with LC3-II-labeled autophagosomes, and significantly increased mitochondrial protein levels, which led to inhibited mitophagy." (PMID 35184140, 2022). "Further therapeutic approaches aimed at modulating PINK1-parkin-mediated mitophagy may help attenuate the mitochondrial pathology associated with prion disease." (PMID 35184140, 2022). "In prion diseases, a transmissible neurodegenerative disease caused by the misfolded and infectious prion protein (PrPSc), expression of both PINK1 and Parkin are elevated, suggesting that PINK1/Parkin mediated mitophagy may also play a role in prion pathogenesis." (PMID 38394123, 2024). "In a prion disease cell model, PINK1/Parkin signaling, specifically PINK1, was required for mitophagy of damaged mitochondria and activation attenuates prion-induced neuronal apoptosis." (PMID 38438964, 2024). "Our results demonstrate a protective role for PINK1/Parkin mitophagy during prion disease, likely by helping to minimize ROS formation via Complex I, leading to slower prion disease progression." (PMID 38394123, 2024). "Mitophagy defects lead to an accumulation of damaged mitochondria and we have demonstrated PINK1-parkin-mediated mitophagy impairment in a prion disease model." (PMID 35184140, 2022). "Obviously then, further studies need to explore the molecular mechanisms regulating PINK1-parkin-mediated mitophagy in prion diseases." (PMID 35184140, 2022). "In this study, we found that PINK1-Parkin-related mitophagy was impaired in the prion disease cell model induced by PrP106-126." (PMID 35184140, 2022). "To further investigate whether mitophagy deficiency in prion diseases is due to PINK1-parkin pathway impairment, we chose two mitophagy activators, UA and NMN, that can activate the PINK1-parkin pathway." (PMID 35184140, 2022). "Given the parkin/ PINK1 protein interaction in which parkin recruitment to mitochondria depends on PINK1, we sought to identify PINK1’s role in parkin recruitment and mitophagy in prion disease." (PMID 35184140, 2022). "Thus, PINK1 is required for parkin to recruit to the mitochondria and mediate mitophagy in a prion disease model." (PMID 35184140, 2022). "Whereas the predominant pathogenic mutations in both SNCA and LRRK2 result in autosomal dominant pattern similarly to inherited forms of human prion diseases, other mutations (e.g., PARK2, PARK7, and PARK6) that involve PRKN, DJ-1, and PINK1 genes result in autosomal recessive patterns." (PMID 34360787, 2021). "Taken together, our data support a protective role for mitophagy in prion disease and are inconsistent with the hypothesis that the elevated levels of PINK1 and Parkin observed during prion disease are indicative of excessive mitophagy that exerts a negative effect on prion disease outcome." (PMID 38394123, 2024). "Therefore, PINK1-parkin-mediated mitophagy may be a potential therapeutic target for prion diseases." (PMID 35184140, 2022). "Since our data suggest that PINK1/Parkin mediated mitophagy is protective during prion infection, it’s possible that prion disease would progress even faster if mice were ablated for MUL1 or Nix, in addition to PINK1 or Parkin." (PMID 38394123, 2024).
prion disease (continued). "Furthermore, since prion disease in mice largely recapitulates prion disease in humans with regard to clinical signs, pathology, and PrPSc properties, it is reasonable to assume that PINK1 and Parkin may exert a similar protective effect on human forms of prion disease such as CJD." (PMID 38394123, 2024). "We have now shown that lack of expression of either PINK1 or Parkin leads to a more rapid progression of prion disease, with similar prion disease incubation times in mice ablated for either protein." (PMID 38394123, 2024). "We have also found that faster prion disease incubation times correlated with increased mitochondrial respiration in prion infected mice lacking the molecule SARM1, a protein that may also be involved in the PINK1/Parkin pathway of mitophagy." (PMID 38394123, 2024). "Since the PINK1/Parkin pathway can regulate mitochondrial dynamics by promoting mitochondrial fission via the expression level of PINK1, we hypothesized that the lack of this pathway would exacerbate the disruption to mitochondrial dynamics observed during prion disease." (PMID 38394123, 2024).